BAZ1A (bromodomain adjacent to zinc finger domain 1A)
Description:
Regulatory subunit of the ATP-dependent ACF-1 and ACF-5 ISWI chromatin remodeling complexes, which form ordered nucleosome arrays on chromatin and slide edge- and center-positioned histone octamers away from their original location on the DNA template to facilitate access to DNA during DNA-templated processes such as DNA replication, transcription, and repair. Both complexes regulate the spacing of nucleosomes along the chromatin and have the ability to slide mononucleosomes to the center of a DNA template in an ATP-dependent manner. The ACF-1 ISWI chromatin remodeling complex has a lower ATP hydrolysis rate than the ACF-5 ISWI chromatin remodeling complex. Has a role in sensing the length of DNA which flank nucleosomes, which modulates the nucleosome spacing activity of the ACF-5 ISWI chromatin remodeling complex. Involved in DNA replication and together with SMARCA5/SNF2H is required for replication of pericentric heterochromatin in S-phase. May have a role in nuclear receptor-mediated transcription repression.
Synonyms: hACF1; WCRF180; ACF1; WALp1
Tractability: Small molecule: a high-quality ligand is known. PROTAC: UniProt records ubiquitination sites on it; ubiquitination databases record sites on it; its protein half-life has been measured; a small molecule that binds it is known.
Target class: Epigenetic regulator; Bromodomain; Reader
Gene: Protein-coding gene on chromosome 14 (34,752,028 to 34,875,647, reverse strand). Ensembl gene ENSG00000198604.
Subcellular location: Nucleus
Gene Ontology:
Molecular function: protein binding; DNA binding; histone acetyltransferase activity
Biological process: chromatin remodeling; DNA-templated DNA replication; nucleosome assembly; positive regulation of DNA replication; regulation of DNA replication; regulation of DNA-templated transcription; regulation of heterochromatin formation; regulation of transcription by RNA polymerase II
Cellular component: ACF complex; CHRAC; nucleus; pericentric heterochromatin; nuclear chromosome
Genetic constraint (gnomAD): Loss-of-function variants: 47 observed, 159.57 expected, observed/expected ratio (o/e) 0.29, 90% interval 0.23 to 0.38. The upper end of that interval is the gene's LOEUF score, 0.38, which puts it in group 1 of 6, group 1 being the genes least tolerant of losing a copy. Missense variants: 1,191 observed, 1,704.9 expected, observed/expected ratio (o/e) 0.7, 90% interval 0.67 to 0.73. Synonymous variants: 515 observed, 584.99 expected, observed/expected ratio (o/e) 0.88, 90% interval 0.82 to 0.95.
Homologues: Orthologues: chimpanzee BAZ1A (99% identical), macaque BAZ1A (99% identical), dog BAZ1A (95% identical), pig BAZ1A (94% identical), rabbit BAZ1A (93% identical), rat Baz1a (87% identical), mouse Baz1a (87% identical), guinea pig BAZ1A (87% identical), tropical clawed frog baz1a (61% identical), Drosophila melanogaster Acf (21% identical), zebrafish baz1a (20% identical), Caenorhabditis elegans baz-2 (15% identical). Paralogues in human: BAZ2B (21% identical), BAZ2A (18% identical), BAZ1B (17% identical), BPTF (13% identical), BRD4 (8% identical), CECR2 (7% identical), KAT2A (6% identical), BRDT (6% identical), BRD2 (6% identical), KAT2B (6% identical), BRD3 (5% identical).
Diseases named in the same sentence as BAZ1A in open-access papers:
BAZ1A is named in the same sentence as 32 diseases in open-access papers, as found by Europe PMC text mining. Sharing a sentence is not in itself a finding about the gene and the disease. The quoted sentences say what the papers report.
depression (3 papers, 2020 to 2022). "Together, these findings suggest that changes induced by depression-like models are specifically associated with the ACF complex’s BAZ1A accessory subunit." (PMID 32957495, 2020). "They identified increases in BAZ1A mRNA and protein correlated with depression in humans and depression-related behaviors in mice." (PMID 32957495, 2020). "Given that the overexpression of BAZ1A and SMARCA5 together but not individually results in a susceptibility phenotype after subthreshold training, it is possible that the BAZ1A-SMARCA complex is instrumental in regulating the formation of depression-like behaviors." (PMID 32957495, 2020).
prostate carcinoma (3 papers, 2021 to 2024). A carcinoma that arises from epithelial cells of the prostate gland. "The intriguing finding that SFN and 6-SFN caused alternative splicing of BAZ1A in colon cancer cells extended prior observations with SFN in a preclinical model of prostate cancer." (PMID 39112459, 2024). "Another unreported finding in SFN-treated human colon cancer cells was the alternative splicing of BAZ1A, extending prior observations on exon skipping/inclusion in a mouse model of prostate cancer after feeding SFN in the diet." (PMID 39112459, 2024). "In African American prostate cancer cohorts, BAZ1A expression was reduced and affected vitamin D receptor-dependent gene expression and disease progression." (PMID 39112459, 2024). "We identified reduced expression of the chromatin remodeler, BAZ1A, in three AA prostate cancer cohorts as well as RC43T compared with RC43N." (PMID 37082578, 2023). "Our study identified that genomic ancestry drives the VDR complex composition, genomic distribution, and transcriptional function, and is disrupted by BAZ1A and illustrates a novel driver for AA prostate cancer." (PMID 37082578, 2023). "Together, these approaches revealed that VDR signaling qualitatively and quantitatively differed between AA and EA cells, and that BAZ1A expression in AA prostate cancer regulated the capacity of the VDR to control immunomodulatory and circadian signaling." (PMID 37082578, 2023). "TCGA analyses identified a potential role for altered expression of the BAZ1A/SMARCA5 SWI/SNF complex, and this was replicated in another AA EA prostate cancer cohort." (PMID 37082578, 2023). "Our data perhaps suggest in RC43N, there is an 1α,25(OH)2D3-autoregulatory mechanism for BAZ1A/SMARCA5 expression and this function that is corrupted in RC43T, and AA prostate cancer." (PMID 37082578, 2023). "Finally, partial correlation analyses established that BAZ1A and components of the VDR complex identified by RIME significantly strengthened the correlation between VDR and target genes in AA prostate cancer only." (PMID 37082578, 2023). "The ISWI subunit BAZ1A was recently discovered as a regulator of cellular senescence, and the related BAZ2A subunit is also known to be overexpressed in prostate cancer, where it may be involved in prostate cancer metastatic regulation." (PMID 34298819, 2021).
Azoospermia (2 papers, 2013 to 2025). Absence of any measurable level of sperm,whereby spermatozoa cannot be observed even after centrifugation of the semen pellet. "Male mice with a knockout of Baz1a, a protein responsible for chromatin remodeling, exhibit widespread gene expression abnormalities contributing to impaired spermatogenesis or azoospermia." (PMID 40391511, 2025). "Interestingly, human BAZ1A was down-regulated in testis tissue displaying round spermatid maturation arrest, isolated from infertile men with azoospermia." (PMID 24244200, 2013).
colon cancer (2 papers, 2021 to 2024). "We observed that several of the phenotypic and molecular changes associated with BAZ1A interference were recapitulated for BAZ2A in colon cancer cells." (PMID 39112459, 2024). "Because BAZ1A is associated with CCAR2 in SFN-treated colon cancer cells, and CCAR2 is part of the DBIRD complex that regulates alternative mRNA splicing, the corresponding molecular targets were examined mechanistically." (PMID 39112459, 2024). "In HCT116 and metastasis-lineage SW620 colon cancer cell lines, shRNA-mediated KD of BAZ1A induced PARP cleavage and pH2AX protein levels markedly, indicative of apoptosis and increased DNA damage, respectively." (PMID 39112459, 2024). "In a well-characterized xenograft model using immunodeficient mice, the growth of implanted BAZ1A knockout colon cancer cells was reduced compared to the control group, as evidenced by the significantly smaller tumor volumes over time." (PMID 39112459, 2024). "Interference with BAZ1A expression reduced the viability of colon cancer cells while increasing pH2AX, cleaved PARP, p16 and β-galactosidase activity." (PMID 39112459, 2024). "Public databases were examined and revealed high BAZ1A expression in the majority of colorectal cancer patients, which was corroborated in a panel of human colon cancer cell lines." (PMID 39112459, 2024). "In conclusion, BAZ1A plays a crucial role in regulating the DNA damage response in colon cancer cells, and an alternatively spliced isoform was markedly less effective in DNA repair, enhancing chemosensitivity to DNA-damaging agents." (PMID 39112459, 2024). "The present investigation sought to clarify the functional consequences of BAZ1A alternative splicing in human colon cancer cells in the regulation of DNA damage response." (PMID 39112459, 2024). "We postulated that the different isoforms of BAZ1A might exert competitive effects in colon cancer cells." (PMID 39112459, 2024). "Notably, almost 100% of colorectal cancer patients had BAZ1A detectable in tumor samples (red bar), with high BAZ1A immunopositivity in colon cancer tissue microarrays compared with normal colon samples." (PMID 39112459, 2024). "This might provide a clue to the phenotypic outcomes in colon cancers following BAZ1A interference, disrupting the activity of ATP-utilizing chromatin assembly and remodeling factor (ACF) complexes." (PMID 39112459, 2024). "This investigation identified BAZ1A as a critical regulator of the DNA damage response, apoptosis, and senescence in human colon cancer cells, consistent with the diverse roles of BAZ family members and other chromatin remodeling factors in physiology and pathophysiology." (PMID 39112459, 2024). "In colon cancer cells treated as reported with SFN or 6-SFN, primers designed to detect alternative splicing of BAZ1A around exon 13 identified an increase in a 288-bp PCR product relative to the 384-bp product, indicative of exon exclusion." (PMID 39112459, 2024). "In colon cancer cells, SFN treatment increased expression of the DBIRD complex members and demonstrated a requirement for CCAR2 in the BAZ1A splicing mechanism." (PMID 39112459, 2024). "In colon cancer cells treated with the deacetylase inhibitor sulforaphane (SFN), acetylation of CCAR2 in the C-terminus established an acetyl ‘switch’ site, whereas acetylation in the N-terminus provided recognition motifs for the bromodomains of BAZ1A and ASH1-like protein (ASH1L)." (PMID 39112459, 2024). "In rescue experiments, a short isoform of BAZ1A that was associated with alternative splicing by the DBIRD complex failed to restore DNA repair activity in colon cancer cells and maintained chemosensitivity to phleomycin treatment, unlike the full-length BAZ1A." (PMID 39112459, 2024).
colon cancer (continued). "For example, the drug mesalazine, used to treat inflammatory bowel disease but with an apoptosis-inducing and chemopreventative effect in colon cancer; DTI-Voodoo predicts mesalazine to interact with five proteins with PHD-type zinc finger domain: BRPF1, TRIM33, BAZ1A, RSF1 and DPF2." (PMID 34320178, 2021).
infertile (2 papers, 2013 to 2022). "The zinc finger and bromo-domain protein ACF1/BAZ1A, a component of ISWI, binds to the chromatin remodeler SNF2H and plays an essential role during post-meiotic spermiogenesis, as evidenced by its deletion resulting in infertility with increased DNA damage and spermiation defects." (PMID 35813619, 2022).
lung carcinoma (2 papers, 2017 to 2020). "Three genes (TET1, ARID1B, and BAZ1A) are highly mutated in breast and lung cancer types, whereas TET1, IDH2, and ARID1B were also among the top genes altered in several cancer types, further corroborating their putative role as cancer drivers." (PMID 32963031, 2020).
breast carcinoma (1 paper, 2024). "Upregulation of BAZ1A in HER2+ breast cancer patients was associated with poor overall survival, and mutation of BAZ1A was documented in uterine carcinosarcoma." (PMID 39112459, 2024).
breast invasive carcinoma (1 paper, 2021). "Through TCGA database analysis, we found that BAZ1A, CHRAC1 and POLE3 are simultaneously up-regulated in a variety of tumors, such as esophageal carcinoma (ESCA), liver hepatocellular carcinoma (LIHC), STAD, breast invasive carcinoma (BRCA), etc.." (PMID 34736517, 2021).
colon adenocarcinoma (1 paper, 2024). "Public databases revealed BAZ1A expression in human colon adenocarcinoma (COAD) and other cancer types." (PMID 39112459, 2024).
colorectal cancer (1 paper, 2024). A primary or metastatic malignant neoplasm that affects the colon or rectum. "We sought to clarify the roles of BAZ1A in the etiology of colorectal cancer, including the mechanisms of its alternatively spliced variants." (PMID 39112459, 2024). "The focus of this work was on BAZ1A, but additional experiments were conducted to draw mechanistic insights into other BAZ family members in colorectal cancer." (PMID 39112459, 2024). "However, SMARCA1 was absent in the colon, according to protein expression data from the Human Protein Atlas (accessed 6/28/2024), underscoring the specific partnership between BAZ1A and SMARCA5 in colorectal cancer." (PMID 39112459, 2024).
liver cancer (1 paper, 2024). An epithelial or non-epithelial malignant neoplasm that arises from the liver. "BAZ1A was highly expressed in liver cancer tissues relative to the adjacent cancer tissues in 30 samples." (PMID 38433277, 2024).
male infertility (1 paper, 2013). The inability of the male to effect fertilization of an ovum after a specified period of unprotected intercourse. "Fifteen Baz1a−/− males bred with wild-type females for eight weeks produced no pups despite the presence of copulatory plugs, indicative of male infertility." (PMID 24244200, 2013).
psoriasis (1 paper, 2014). An autoimmune condition characterized by red, well-delineated plaques with silvery scales that are usually on the extensor surfaces and scalp. "In addition, we observed some evidence consistent with an association between CD and a SNP in the promoter of the BAZ1A gene, at the end of a region included on the ImmunoChip in order to fine-map a psoriasis susceptibility locus." (PMID 25259511, 2014).
schizophrenia (1 paper, 2013). A major psychotic disorder characterized by abnormalities in the perception or expression of reality. "Also, we observed three SZUP genes (BAZ1A, TMEM176A, and FTL) in this module in the control network, but not in the schizophrenia network." (PMID 24070017, 2013).
teratospermia (1 paper, 2013). "Sperm from total epididymides of Baz1a−/− mice displayed an array of aberrant head morphologies (teratospermia), all of which lacked a normal hook characteristic of wild-type sperm heads." (PMID 24244200, 2013).
tumor (13 papers, 2013 to 2026). "In the clinical setting, patients with tumor-associated BAZ1A-SF might be more responsive to standard of care DNA-damaging agents, offering promising new avenues for precision oncology." (PMID 39112459, 2024). "Another possibility is that DSB repair defects could be tied to presence of other mutations that sensitize the tumor-derived human cell lines studied to BAZ1A depletion." (PMID 24244200, 2013). "Immunoblotting of tumor xenografts recovered at the end of the experiment confirmed the effective KD of BAZ1A and the corresponding increase in DNA damage and senescence markers, such as pH2AX and p16." (PMID 39112459, 2024). "The corresponding molecular changes resulted in tumor growth inhibition when BAZ1A-knockout cells were implanted into nude mice." (PMID 39112459, 2024). "Consistent with this notion, heterochromatic foci were reduced significantly in BAZ1A-null tumor xenografts recovered at the end of the study." (PMID 39112459, 2024). "Apart from CTNNB1, we’ve identified several cancer-related gene mutations, including PML, HSP90AA1, BAZ1A, ARHGAP5, LHFPL6 in the primary tumor of HB, which may also contribute to the carcinogenesis of HB." (PMID 35860547, 2022). "RNAi depletion studies in cultured, tumor-derived human cells indicate that Baz1a facilitates replication through heterochromatic DNA, contributes to repression of vitamin D3 receptor-regulated genes, and promotes DNA double-strand break (DSB) repair and the G2/M DNA damage checkpoint." (PMID 24244200, 2013). "RNAi directed against BAZ1A transcripts in cultured, tumor-derived human cells caused defects in DSB repair via non-homologous end-joining (NHEJ) and homologous recombination (HR)." (PMID 24244200, 2013). "Focally deleted regions identified the tumour-suppressor genes RHOA at 3p21, CDKN2A and CDKN2B at 9p21, RAD51B, MAX, DICER1, BCL11B, NKX2-1, CCNB1IP1 and BAZ1A at 9q33." (PMID 34980126, 2022). "Only for five genes, namely KAT2A, SMARCA4, BAZ1A, ATAD2 and TRIM28, we observed consistently higher levels and for two genes—KAT2B and SMARCA2—lower levels, respectively, regardless of the tumor type." (PMID 35049055, 2022).
cancer (11 papers, 2015 to 2025). A tumor composed of atypical neoplastic, often pleomorphic cells that invade other tissues. "Knockdown (KD) of BAZ1A triggered senescence-associated phenotypes in various human cancer cell lines due to increased SMAD Family Member 3 (SMAD3) expression promoting p21 activation." (PMID 39112459, 2024). "Given the current interest in RNA splicing deregulation and cancer etiology, additional mechanistic studies are warranted with new lead compounds targeting BAZ1A, and other members of the BAZ family, with a view to improved therapeutic interventions." (PMID 39112459, 2024). "Canonical CTNNB1 p.Ser45Pro missense mutation, as well as several other cancer-related genes (e.g., PML, HSP90AA1, BAZ1A, ARHGAP5, LHFPL6), were detected in the PT sample." (PMID 35860547, 2022). "Understanding the precise roles of BAZ1A and its isoforms could lead to more effective cancer treatments, thereby optimizing patient outcomes." (PMID 39112459, 2024). "In addition, BAZ1A complexes with SOX2 to drive the enhancer-promoter interaction and facilitate the recruitment of BRD4, thereby activating the expressions of cancer stem cells (CSCs)-related signature." (PMID 40204721, 2025). "Polymorphisms were also found in other canonical cancer-related genes, including SLC37A3, BAZ1A, SRP54, MYH1 and ABCC1, but were not directly involved in MASLD pathogenesis." (PMID 38540416, 2024).
BAZ1A also shares sentences with these, for which no sentence is quoted: atherosclerosis (1 paper); bone osteosarcoma (1); breast tumors (1); carcinosarcoma (1); duodenal cancer (1); esophageal squamous cell carcinoma (1); fibrosarcoma (1); head and neck squamous cell carcinoma (1); Hypoalbuminemia (1); inflammatory bowel disease (1); intellectual disabilities (1); lung adenocarcinoma (1); mood disorder (1); neuroblastoma (1); uterine carcinosarcoma (1).